RAD51 (RAD51 recombinase)
Diseases named in the same sentence as RAD51 in open-access papers (continued):
Sharing a sentence is not in itself a finding about the gene and the disease.
lung carcinoma (continued). "For instance, cisplatin induces the expression of the TLS polymerase REV3 in lung cancer cell lines leading to cisplatin resistance, while cisplatin-resistant lung cancer cells show significant upregulation of the DSB repair genes RAD51, RAD52, and CHK2." (PMID 36980782, 2023). "Overall, our findings indicated that ANRIL reduces Rad51 and BRCA1 expression by targeting miR-7-5p/PARP1, which ultimately leads to radiotherapy resistance in lung cancer cells." (PMID 36755223, 2023). "In the three lung cancer lines analysed herein, radiation induced a rapid, dose‐dependent formation of ɣ‐H2AX and Rad51 foci." (PMID 34636174, 2022). "Among these cancer types, RAD51 was strongly correlated to the stemness in 8 cancer types, such as breast invasive carcinoma (BRCA), esophageal carcinoma (ESCA), lung cancer (LUAD&LUSC), and stomach adenocarcinoma (STAD), where the coefficients were over 0.5." (PMID 35359409, 2022). "The FACS analysis revealed that RAD51 inhibitor treatment increased PD-L1 expression in TNBC (MDA-MB-231), lung cancer (A549), pancreatic cancer (KP-4) and colon cancer (HCT 116) cell lines in a dose-dependent manner." (PMID 35646698, 2022). "RAD51 was negatively correlated with many MHC molecules in multiple cancer types, such as adrenocortical carcinoma (ACC) and lung cancer (LUAD&LUSC)." (PMID 35359409, 2022). "The repair kinetics differed between the two human lung cancer lines, with a reduction in γ‐H2AX and Rad51 foci at 4 h after irradiation in A549 cells compared to H460 cells, suggesting faster repair of DSB in A549 cells compared to H460 cells." (PMID 34636174, 2022). "EGFR gene fusions also occur in lung cancer and the most common fusion is EGFR-RAD51, which is a fusion between the EGFR TKD and RAD51, a DNA damage response protein." (PMID 34867402, 2021). "We further analyzed representative HRR and NHEJ marker proteins, including the levels of BRCA1 and RAD51 (for HRR) and the level of phosphorylated DNA-PKcs at T2609 (for NHEJ), in four lung cancer cell panels with different FHIT statuses and two FHIT-isogenic cell pairs." (PMID 39762409, 2025). "Importantly, the knockdown of FBXO22 significantly reduced the responsiveness of lung cancer cells to deguelin, suggesting that deguelin functions in an FBXO22/Rad51-dependent manner." (PMID 38296976, 2024). "Three lung cancer lines (A549, H460 and LL2) were irradiated with different X‐ray doses or X‐radiated with a 5 Gy dose and examined at different time‐points post‐irradiation for DNA DSB in the form of γ‐H2AX and Rad51 foci." (PMID 34636174, 2022). "For instance, RAD51 and SPAG5 were identified to be associated with poor survival in patients with early stage LUAD but their function in lung cancer has not been extensively characterized." (PMID 36304306, 2022). "Because γ-H2AX foci and Rad51 foci were co-localized in the cells treated with VAL-083, VAL-083–induced DNA DSBs were suggested to be repaired by HR, which was consistent with the previous report using lung cancer." (PMID 34073837, 2021). "Expression of Rad51 had an important impact on lung cancer survival regardless of the histological cell type." (PMID 15956972, 2005). "However, the Rad51-positive foci, in comparison to the H2AX-positive but Rad51-negative foci, obviously have more correlative power for the radiation sensitivity of lung cancer cell lines." (PMID 15785736, 2005).
pancreatic cancer (52 papers, 2005 to 2025). "In this study, we examined the correlation between RAD51 and KRAS mutation and the impact of RAD51 on cell proliferation and glucose metabolism reprogramming in pancreatic cancer." (PMID 31889908, 2019). "When KRAS was silenced, RAD51 expression decreased in pancreatic cancer cells lines that harbor KRAS mutation." (PMID 31889908, 2019). "The present study reveals novel roles for RAD51 in pancreatic cancer that are associated with overall survival prediction, possibly through a mechanism involving regulation of aerobic glycolysis." (PMID 31889908, 2019). "Dysregulation of RAD51 is closely associated with tumourigenesis in multiple cancers, including breast, hepatocellular and pancreatic carcinomas, with its overexpression frequently correlating with aggressive tumour behaviour, therapeutic resistance and poor prognosis." (PMID 41350246, 2025). "In the present study, our results demonstrated that introduction of KRAS G12D mutation, a mutation frequently observed in pancreatic cancer, could increase Rad51 mRNA and protein expression levels." (PMID 31889908, 2019). "Thus, uncovering the role of RAD51 in metastasis of pancreatic cancer and elucidating the underlying mechanism might lead to inhibition of metastasis and reversal of chemotherapy and radiotherapy resistance in pancreatic cancer." (PMID 31889908, 2019). "Along this line, RAD51 was found to be overexpressed in many solid tumors, including breast, lung, and pancreatic cancer." (PMID 41463247, 2025). "Pancreatic cancer showed an exceptionally high biallelic loss in HRR genes, with BRCA1, CDK12, FANCC, PPP2R2 A, RAD51 C, RAD51D, RAD52, WRN, and XRCC3 all presenting 100% biallelic loss." (PMID 40420266, 2025). "In pancreatic cancer, the role of RAD51 in PDAC cell proliferation and cancer development has rarely been described, although KRAS mutation has been reported to increase RAD51 expression." (PMID 36262061, 2023). "Increased expression of Rad51 in the homologous recombination repair of a DNA double-strand break (DSB) has been demonstrated in pancreatic cancer." (PMID 35008384, 2022). "Increased expression of Rad51 in the homologous recombination repair of a DNA double-strand break has been demonstrated in pancreatic cancer." (PMID 35008384, 2022). "Pretreatment with gemcitabine had a restraining effect on the homologous DNA recombination repair (HRR) of DNA crosslinking, inhibiting the function of Rad51, of which expression is found to be increased in pancreatic cancer." (PMID 35008384, 2022). "Of all RAD51 paralogs, the germline RAD51C and RAD51D variants can be found in both pancreatic cancer and prostate cancer, at a rate lower than 0.5%." (PMID 35563100, 2022). "The compound 1,2,4-Trimethyl-3-nitrobicyclo [3.3.1]nonan-9-one shows binding features with the cancer target protein RAD51 similar to the FDA approveddrug of 5-Flurouracil for further consideration in the context of pancreatic cancer drug discovery." (PMID 35540702, 2021). "It is of note that RAD51 expression is strongly increased in breast, thyroid or pancreatic cancer and that its overexpression is strongly correlated with poor prognosis." (PMID 34208195, 2021). "Since these various roles of RAD51 in DNA damage are closely related to genome stability, the normal cell cycle, and immunity, RAD51 has been considered a promising therapeutic target for various cancers including lung, breast, melanoma, and pancreatic cancer." (PMID 34067336, 2021). "Our mechanism studies indicated that RAD51 promoted pancreatic cancer progression by enhancing aerobic glycolysis via HIF1α." (PMID 31889908, 2019). "Collectively, our findings identified novel roles for RAD51 in pancreatic cancer in relation to prediction of overall survival, as well as the possible underlying mechanisms." (PMID 31889908, 2019). "Our present study revealed that Rad51 is a predictive marker for overall survival in pancreatic cancer." (PMID 31889908, 2019).
pancreatic cancer (continued). "As an important component of the DNA damage repair machinery, RAD51 has seldom been investigated in pancreatic cancer." (PMID 31889908, 2019). "Collectively, these results suggest that RAD51 can positively regulate pancreatic cancer cell proliferation." (PMID 31889908, 2019). "To validate the role of RAD51 expression in pancreatic cancer prognosis, we used TCGA database to examine the correlation between RAD51 expression and overall survival of pancreatic cancer patients." (PMID 31889908, 2019). "It was observed that silencing RAD51 significantly increased intracellular ROS production in pancreatic cancer cells." (PMID 31889908, 2019). "To assess the impact of RAD51 on pancreatic cancer cell proliferation, we silenced RAD51 expression in PANC-1 and MIA PaCa-2 cells." (PMID 31889908, 2019). "Colony formation assays were also performed to further validate the role of RAD51 in pancreatic cancer cell proliferation." (PMID 31889908, 2019). "In pancreatic cancer cells, RAD51 positively regulated cell proliferation, decreased intracellular reactive oxygen species (ROS) production and increased the HIF1α protein level." (PMID 31889908, 2019). "RAD51 is a well-characterized factor in the DNA damage and repair process; however, its role in pancreatic cancer has scarcely been reported." (PMID 31889908, 2019). "TCGA (The Cancer Genome Atlas) dataset analysis was used to examine the impact of RAD51 expression on overall survival of pancreatic cancer patients." (PMID 31889908, 2019). "In this report, we found that elevated RAD51 expression predicted worse prognosis in pancreatic cancer patients." (PMID 31889908, 2019). "Mechanistically, KLF5 promoted expression of E2F1, cyclin D1 and Rad51, while inhibiting expression of p16 in pancreatic cancer cells." (PMID 31327760, 2019). "Others reported the gemcitabine + olaparib combination induced RAD51 focus formation in pancreatic cancer cells which was attenuated upon co-treatment with CHK1 inhibitors (MK-8776 or prexasertib)." (PMID 31492187, 2019). "Recently, Narayanaswamy and colleagues reported prexasertib blocked nuclear localization of Rad51 in pancreatic cancer cell lines in response to DNA damage by gemcitabine." (PMID 29340034, 2017). "A Wee-1 inhibitor, AZD1775, also attenuated Rad51 nuclear localization in pancreatic cancer cells, and resulted in sensitization to DNA damaging effects from radiation and PARPi." (PMID 29340034, 2017). "AZD7762, a Chk1 inhibitor prevents the formation of Rad51 foci in pancreatic carcinoma cells and also leads to persistent γ-H2AX in response to γ-radiation." (PMID 25909291, 2015). "The recombination factor Rad51 is highly expressed in pancreatic adenocarcinoma, and Rad51 autoantibodies have been observed in 7% of patients with pancreatic cancer." (PMID 18769604, 2006). "Furthermore, RAD51 promotes cancer progression through distinct mechanisms in pancreatic cancer, cervical squamous cell carcinoma, lung adenocarcinoma, malignant glioma and invasive ductal breast carcinoma." (PMID 41350246, 2025). "For example, RAD51 was reported as prognostic biomarkers for colon cancer and pancreatic cancer." (PMID 35359409, 2022). "RAD51 is highly expressed in various cancers including breast, lung, and pancreatic cancers." (PMID 34067336, 2021). "Furthermore, this overexpression was shown in 66% of pancreatic cancer, and functional analysis suggested that RAD51 overexpression enhanced the cell survival after DSBs damage." (PMID 31973027, 2020). "Whether KLF5 binds to the Rad51 promoter to stimulate its gene expression and whether Rad51 can enhance the ability of pancreatic cancer cells to resist survival pressure from chemotherapeutic agents such as gemcitabine remain to be determined." (PMID 31327760, 2019). "Pancreatic cancer patients with higher levels of RAD51 exhibited worse survival." (PMID 31889908, 2019).
pancreatic cancer (continued). "However, the role of RAD51 in pancreatic cancer cell proliferation and other hallmarks has rarely been reported." (PMID 31889908, 2019). "Moreover, Rad51 positively regulates aerobic glycolysis in pancreatic cancer cells by regulating HIF1α protein stability and the HIF1α-targeted transcriptional program." (PMID 31889908, 2019). "The present study may shed light on approaches to prevent chemotherapy and radiotherapy resistance in pancreatic cancer by targeting the RAD51/HIF1α axis." (PMID 31889908, 2019). "The OCR values in RAD51-silenced pancreatic cancer cells were then measured." (PMID 31889908, 2019). "Therefore, the present results indicate that KRAS/MEK/ERK activation can increase RAD51 expression in pancreatic cancer cells." (PMID 31889908, 2019). "Additionally, pancreatic cancer cells have been shown to accurately reflect their malignant phenotype, in which Rad51 is overexpressed, only when cultured in a three dimensional matrix." (PMID 22174876, 2011). "Furthermore, we also investigated RAD51 inhibition in context of pancreatic cancer cell." (PMID 35646698, 2022). "Based on the available literature, it is estimated that 17 to 25% of pancreatic cancer harbor somatic PVs in one of the genes involved in DDR, mainly those implicated in homologous recombination DNA damage response and repair (HR), such as BRCA1, BRCA2, ATM, PALB2, ATRX, and RAD51." (PMID 35563100, 2022). "Importantly, the proton-specific sensitization as well as the reduction in Rad51 protein levels by HSP90 inhibition match previous findings generated with carbon irradiation but are partially contradicted by findings in 3D pancreatic cancer cultures." (PMID 35410422, 2022). "As VPA or TSA reduce CHK1 and RAD51, which is an HR repair molecule, their combination with AZD2461 could underlie the stronger DNA damage and the increased cytotoxicity observed against pancreatic cancer cells." (PMID 35216385, 2022). "Moreover, microarray analysis showed an increased RAD51 expression in pancreatic carcinoma." (PMID 31973027, 2020). "Thus, we assessed the influence of RAD51 on glycolysis in pancreatic cancer cells." (PMID 31889908, 2019). "Moreover, how RAD51 expression is regulated in pancreatic cancer has seldom been reported." (PMID 31889908, 2019). "Intriguingly, the immunofluorescence assay revealed a reduction in the foci of BRCA1 and Rad51, two crucial proteins involved in DNA repair, in NLRP4-knockdown pancreatic cancer cells 6 h after olaparib removal." (PMID 39187531, 2024). "Using cellular assays (BxPC-3, pancreatic cancer), we show that a myristoylated BRC4 (designed for a more efficient cell entry) abolished the formation of nuclear RAD51 foci." (PMID 35955488, 2022). "Pretreatment by Rad51-inhibitory substances such as gemcitabine followed by arterial chemotherapy using antineoplastic agents causing DNA, DSB, or DNA crosslink might be more beneficial for patients with locally advanced pancreatic cancers than conventional treatments." (PMID 35008384, 2022). "BBR caused inhibitory effects in pancreatic cancer cells on the expression of Rad51 and the upregulation of PARP expression compared with control pancreatic cancer cells." (PMID 36144625, 2022). "BBR showed inhibitory effects in pancreatic cancer cells (PANC-1, AsPC-1, and MIA-PaCa-2) on the expression of Rad51 and the upregulation of PARP expression compared with control pancreatic cancer cells." (PMID 34885950, 2021). "Thus, increased RAD51 expression in pancreatic cancer might regulate metastasis." (PMID 31889908, 2019). "In this report, we provide evidence that RAD51, regulated by KRAS, promotes pancreatic cancer cell proliferation." (PMID 31889908, 2019). "When pancreatic cancer cells were treated with UO126, we observed a decrease in RAD51 mRNA and protein levels." (PMID 31889908, 2019).
pancreatic cancer (continued). "Indeed, we found that an increased degradation via proteasome was responsible for CHK1 and RAD51 down-regulation following the VPA and TSA treatment of pancreatic cancer cells." (PMID 35216385, 2022). "Overexpressionof RAD51 occurs in variety of cancers, which includes pancreatic cancer and is a negative prognostic marker for the survival of various cancer patients." (PMID 35540702, 2021). "We document the molecular docking and GC-MS data for the inhibition of RAD51 expression by 1,2,4-Trimethyl-3-nitrobicyclo [3.3.1] nonan-9-one from C. inerme in the context of pancreatic cancer drug discovery." (PMID 35540702, 2021). "The authors determined on human pancreatic cancer and osteosarcoma cell line models that CHK1 inhibition affected the de novo formation of RAD51 oligomers but not their stability." (PMID 34208195, 2021). "A recently published study combining two parallel phase 2 clinical trials assessed olaparib monotherapy in 24 patients with previously treated pancreatic cancer and non-BRCA HR gene alterations (somatic BRCA, germline or somatic ATM, PALB2, ARID1A, PTEN, RAD51, CCNE and FANCB)." (PMID 34572943, 2021).